MITF (melanocyte inducing transcription factor)
Diseases named in the same sentence as MITF in open-access papers (continued):
Sharing a sentence is not in itself a finding about the gene and the disease.
melanoma (continued). "The leading hypothesis in the field is that high MITF expression (MITFhigh) is associated with a differentiated and proliferative phenotype, whereas low MITF expression (MITFlow), is associated with a dedifferentiated, invasive, apoptosis-resistant, and melanoma-initiating cell phenotype." (PMID 33276788, 2020). "For instance, MITF gene is known to be involved in human melanomas, as indicated by the genetic amplification of MITF locus in most tumors and gene mutations in some." (PMID 33490073, 2020). "MITF is also considered as a lineage-specific oncogene highly expressed in human melanomas that contributes to tumorigenesis, by promoting reversible and functional reprogramming of signaling pathways in melanoma." (PMID 33167306, 2020). "The role of MITF-PGC1α axis was shown to be responsible for mitochondrial biogenesis leading to consequent changes in ROS level in melanoma cells." (PMID 33091721, 2020). "It has been also reported that MITF is phosphorylated by AKT at serine 510 in melanoma cells, leading to an unstable transcription factor and decreased tyrosinase expression." (PMID 32674468, 2020). "Collectively, these results indicate that ACF is likely to decrease MITF levels in melanoma cells by modulating the phosphorylation of ERK1/2 and CREB in a mechanism independent of ATF4." (PMID 33396270, 2020). "Altogether, these results show that even though the COX-2/PGE2 pathway has been shown to promote EMT in different cancer cell types, it seems to enhance MITF expression in melanoma cells." (PMID 33121001, 2020). "We first found that ANXA1 expression was positively correlated with MITF expression in lung adenocarcinoma (Spearman’s correlation = 0.35, q < 0.001) but negatively correlated with MITF in melanoma (Spearman’s correlation = −0.34, q < 0.001)." (PMID 33293474, 2020). "In particular, it has been reported that miR-137 downregulates MITF expression in melanoma cell lines and its expression has been observed to correlate with the poor survival of melanoma patients at stage IV." (PMID 32013263, 2020). "TFAP2, which promotes melanocyte differentiation by activating a subset of MITF target genes, is frequently lost in melanoma due to silencing by CpG methylation." (PMID 32151278, 2020). "The oncogenic role of MITF in melanoma is well defined, but the function of MITF in the NSCLC is still unclear." (PMID 33293474, 2020). "Exploration of the possible immune exclusion mechanisms at play revealed likely dependency on MITF protein level and PTEN loss‐of‐function events for melanomas unresponsive to immunotherapies (immune‐low)." (PMID 32147909, 2020). "During development of resistance, the MITF-M protein level was substantially diminished in MITF-Mhigh cells and remained low/undetectable in MITF-Mlow melanoma cells." (PMID 31624899, 2020). "In DN and melanomas of our series of MITF+ patients, we found 3 prevalent dermoscopic patterns: unspecific, globular-homogeneous and reticular-homogeneous." (PMID 32054529, 2020). "The MC1R/cAMP/MITF pathway is a key determinant for growth, differentiation, and survival of melanocytes and melanoma." (PMID 32605315, 2020). "Overall, our analysis suggests that the upregulation of HERV-K expression in proliferative melanoma is likely driven at least in part by direct binding of MITF over the LTR5_Hs through the E-box motif." (PMID 33202765, 2020). "The genes for markers melanogenesis tyrosinase (TYR) and transcription factor MiTF (MITF), which are specific for melanoma cells, were observed predominantly in the pool of melanoma cells." (PMID 33182777, 2020). "MITF+ patients tend to develop melanomas and dysplastic nevi with histopathological features, frequency and dermoscopic patterns often different from those prevalent in MITF− patients." (PMID 32054529, 2020). "In the MITF+ group, two patients had amelanotic/hypomelanotic melanomas; both patients carried one red-hair-color (RHC) MC1R variant (R169W, R142H)." (PMID 32054529, 2020).
melanoma (continued). "Melanocyte Inducing Transcription Factor (MITF) expression promotes melanoma cell survival and migration." (PMID 32846966, 2020). "To knockdown (KD) Rec, we designed three RNAi constructs to target the sequence of the ERVK6 locus, for which we observed marks of high transcriptional activity in MITF-High and A375 melanoma cells." (PMID 33202765, 2020). "Knockdown of ANXA1 in pancreatic ductal adenocarcinoma increases cell migration and invasion, but inhibits cell proliferation, which is similar to the phenotype at low levels of MITF in melanoma." (PMID 33293474, 2020). "The level of MITF activity for example, which depends on its expression but also on its post-translational modifications, plays a crucial role in the behavior of melanoma cells." (PMID 31118886, 2019). "We further queried the changes in protein level expression of MITF and a few of its target genes in these melanoma cells, following drug treatment, GH treatment, as well as GHR blockade." (PMID 31547367, 2019). "In the current study, we present in vitro, in vivo, and in silico evidence describing a GH-mediated upregulation of MITF expression and activity, with implications in melanoma drug resistance." (PMID 31547367, 2019). "Transcription factor MITF is appropriate for the identification of melanocytic cells in horse melanoma." (PMID 31717496, 2019). "Here we have identified a new set of 245 candidate melanoma-associated lncRNAs that are targeted by the MITF and SOX10 melanoma transcription factors." (PMID 31881017, 2019). "The most cancer‐specific dysregulated miRNA in melanoma is miR‐211‐5p, which is indeed transcribed by MITF together with its host gene, melastatin (TRPM1), in human melanocytes." (PMID 30499222, 2019). "As autophagy levels have been shown to be high in melanoma, we investigated the involvement of MITF in regulating expression of lysosomal and autophagosomal genes in these tumors." (PMID 30705290, 2019). "The loss of miR-211 results in elevated BRN2 levels and leads to the inhibition of MITF expression and maintenance of melanoma cells in a dedifferentiated, pro-invasive state." (PMID 30866509, 2019). "MITF governs the melanocyte-specific melanin synthesis pathway with tyrosinase as an essential enzyme, and in melanoma it is one of the main drivers of proliferation and invasiveness." (PMID 30823658, 2019). "Both epidermal and dermal Tomato+ cells expressed melanocyte/melanoma markers S100b, Dct, MITF and Sox10." (PMID 31685822, 2019). "MITF is the key regulator of the melanoma phenotypic switch: It transcriptionally regulates the gene set responsible for both proliferative and invasive phenotypes." (PMID 30699982, 2019). "The enforced expression of MITF was demonstrated to induce the differentiation and lower cell proliferation in BRAFV600E mutated melanoma cells, thereby highlighting the equivocal role of MITF in melanoma progression and BRAF inhibitor resistance." (PMID 31416288, 2019). "Here we show that MITF also plays a central role in regulating the autophagy response to starvation in melanoma cells." (PMID 30705290, 2019). "With MITF's central role in melanoma and its link to the MAPK pathway, it is crucial to fully understand the impact that MAPKi have on MITF during treatment." (PMID 30277012, 2019). "This indicates that the expression of genes bound by MITF in melanocytic and melanoma cell lines are positively regulated by MITF in melanoma tumors." (PMID 30705290, 2019). "Significantly, MITF depletion using two different MITF‐specific siRNAs led to reduced SDHB expression in two melanoma cell lines." (PMID 31207090, 2019). "Verification by RT-PCR and immunohistochemistry confirmed upregulation of CD9 and retinoic acid responder 1 gene (RARRES1) in regressive tumors, while MITF was upregulated in progressive melanomas." (PMID 31717496, 2019). "In melanoma, low levels of MITF are accompanied by low levels of ASAH1 expression, which correlates with invasive behavior and worse prognosis." (PMID 31336922, 2019).
melanoma (continued). "In summary, our results show that MITF knockdown decreases the expression of several lysosomal and autophagosomal genes and reduces the autophagic response to starvation in both melanoma cells and primary melanocytes." (PMID 30705290, 2019). "Taken together, these data provide strong evidence that DIRC3 is transcriptionally repressed by SOX10 and MITF in melanoma." (PMID 31881017, 2019). "MITF amplification is frequent in melanoma and particularly common in metastatic forms of the disease where it associates with poor survival." (PMID 31881017, 2019). "Melanocyte/melanoma specific isoform of MITF (M-MITF) is the only isoform of MITF where its expression is under the control of BRAFV600E." (PMID 31416288, 2019). "Our results support this regulatory role and provide a developmental context in vivo to understand why GDF6-activated BMP signaling is able to regulate MITF in melanoma cells." (PMID 31868592, 2019). "To obtain further insight into the mechanism of senescence, we tested the expression of MITF, a master regulator of melanocyte development and a melanoma oncogene, whose silencing has been shown to induce senescence." (PMID 30674989, 2019). "According to the rheostat model, different programs can be executed in melanoma cells depending on MITF activity, and low levels and activity of MITF are connected with an invasive phenotype." (PMID 30866509, 2019). "To complement our studies with primary tumor samples, we also isolated and obtained populations of MITF-positive primary melanoma cells from fresh patient-derived tumors and confirmed that they exhibited high levels of endogenous PANX1 protein." (PMID 30654593, 2019). "MITF is also a major transcriptional regulator of melanoma inhibitor of apoptosis (ML-IAP) expression in melanoma tissues." (PMID 31717496, 2019). "Since recent studies reported that MITF is a crucial target in melanoma therapy, this study focused on the antitumor activity of 23R-AMA." (PMID 30084054, 2019). "Here we reveal a negative regulatory loop between Notch signaling and microphthalmia-associated transcription factor (MITF), the central regulator of melanoma progression and the driver of melanoma plasticity." (PMID 30699982, 2019). "The dependence of MITF upregulation on low ERK activity suggests that in melanomas in which the PAX3/BRN2 rheostat is intact, MITF will be upregulated on treatment with MAPKi." (PMID 30277012, 2019). "Another mutation-independent mechanism that underlies the initiation of melanoma metastasis during the transition from radial to vertical growth involves miR-222/221, NOTCH, and MITF." (PMID 30866509, 2019). "Tight control over MITF expression levels is required for optimal melanoma growth, and while it is well established that the MAPK pathway regulates MITF expression, the actual mechanism is insufficiently understood." (PMID 30277012, 2019). "A correlation between transcript levels of MITF and PGC1α was previously demonstrated in melanoma cells, and this correlation was also confirmed in our study." (PMID 31461993, 2019). "This allows for a deeper understanding of the enigmatic ‘rheostat-model’ of MITF regulation in melanocytes and melanoma and can be validated by future studies." (PMID 31547367, 2019). "In conclusion, it is inferred that 23R-AMA inhibited growth and migration of B16-F10 melanoma by regulating both MITF expression and its activity via regulation of both β-catenin accumulation in the nucleus and the signaling pathway from FAK to ERK." (PMID 30084054, 2019). "Consistent with the results showing changes in MLANA transcript levels, treatment of MITF-Mhigh melanoma cells with vemurafenib or trametinib for 44 h resulted in increased percentages of Melan-A-positive cells." (PMID 31354817, 2019).
melanoma (continued). "Further, GHR and MITF clustered together among the top 20 differentially upregulated genes between human melanoma (metastatic and primary) sample gene expression data extracted from the GSEA7553 set and ranked by high and low PGC1A expression levels." (PMID 31547367, 2019). "Our findings suggest that, once activated, Notch signaling represses MITF signaling to maintain the melanoma invasiveness and metastatic phenotype." (PMID 30699982, 2019). "Depletion of MITF in melanoma cells and melanocytes attenuates the response to starvation-induced autophagy, whereas the overexpression of MITF in melanoma cells increases the number of autophagosomes but is not sufficient to induce autophagic flux." (PMID 30705290, 2019). "One such dynamic change involves the expression of the transcription factor MITF, a crucial regulator of cell survival and proliferation in untreated as well as drug‐addicted acquired resistant melanoma." (PMID 30277012, 2019). "This can be seen in acquired resistant, but drug‐addicted melanoma cells, whose survival in the presence of drug is entirely dependent on the presence of MITF." (PMID 30277012, 2019). "Taken together, our results indicate that in SkMel28 melanoma cells, MITF knockdown decreases autophagosome formation, followed by a reduction in global autophagic degradation." (PMID 30705290, 2019). "This negative feedback loop is likely important in restricting the activity of MITF, and in melanoma cells, enabling cells to maintain proliferation." (PMID 31207090, 2019). "Lastly, one of the highlights of our current study is identification of the effect of GH action in melanoma in promoting MITF-mediated melanogenesis in melanosomes." (PMID 31547367, 2019). "On the other hand, we identified in about 57% of the cell lines, a potent and unique SAB298 function of downregulating MITF, a lineage-transcription factor for melanocytes and melanomas." (PMID 31040916, 2019). "Our current study identifies MITF as a partial mediator of GH-regulated MET upregulation and strongly implicates GH as an upstream effector in promoting MITF-regulated antiapoptotic and pro-survival effect in melanoma." (PMID 31547367, 2019). "These epidermal Mcs, not observed in control mice, also expressed the melanocyte/melanoma markers S100b, Dct, microphthalmia transcription factor (MITF) and Sox10." (PMID 31685822, 2019). "Potent shRNA-driven MITF downregulation was confirmed in both MDA-MB-436 basal breast cancer cells and SK-Mel-28 melanoma cells with known high MITF levels." (PMID 31554806, 2019). "In a panel of MITF-Mhigh melanoma cell lines, these genes were transcriptionally upregulated, except for DMBC17 cells (BRAFWT) treated with vemurafenib." (PMID 31354817, 2019). "Mutating (P2mut) or deleting (∆55) P2 also completely abolished the ability of PAX3 to stimulate transcription from the MITF promoter in melanoma cells." (PMID 30277012, 2019). "At baseline, these three melanoma cell lines exhibited a low AXL/high MITF differentiated genetic signature." (PMID 30953519, 2019). "Multiple promoters of PPARGC1A, a gene encoding PGC1α, are selectively responsive in distinct tissues, and MITF was found to directly stimulate the expression of PGC1α by binding to its promoter region in melanoma cells." (PMID 31461993, 2019). "To verify that MITF can bind to specific melanosomal and lysosomal genes in a human melanoma cell line, we performed ChIP on endogenous MITF in 501Mel cells, followed by qRT-PCR." (PMID 30705290, 2019). "(A-B) Scatterplot of log2 FPKM expression values between IL32 and select immune genes (A) or between the ratio of AXL and MITF log2 FPKM expression values (B) in the melanoma TCGA dataset (n = 479)." (PMID 30953519, 2019). "The patient-derived melanoma cell lines chosen for this study differ in oncogenic mutations in the MAPK/ERK pathway and activity of transcription factor MITF, one of the critical regulators of melanoma phenotype." (PMID 31461993, 2019).
melanoma (continued). "More globally, these analyses validate PSIONIC as a predictive tool to predict TF activity in specific tumor settings, as shown for MITF in basal breast cancer, that expands its role in cancer beyond its known lineage-specific functions in melanoma." (PMID 31554806, 2019). "Analysis of “The Cancer Genome Atlas” (TCGA) melanoma dataset confirmed a positive correlation of MITF-CEACAM1 axis." (PMID 30871206, 2019). "Recently, MITF-M, one of the isoforms of MITF, was reported to be specifically expressed in melanoma cells." (PMID 30084054, 2019). "MITF is a master regulator of melanocytes and a lineage-specific melanoma oncogene, and it is important for cell differentiation, proliferation and survival." (PMID 31461993, 2019). "We observed that MITF knockdown leads to reduced starvation-induced autophagy degradation in both melanocytes and melanoma cells, presumably because of less autophagosomal formation." (PMID 30705290, 2019). "By western blot analysis in 12 melanoma cell lines we tested expression of NFATc2, of several EMT-related proteins as well as of AXL and MITF, the prototypic markers of the alternative invasive/proliferative transcriptional programs of melanoma." (PMID 30710146, 2019). "miR-148 has been reported to negatively regulate MITF expression in melanoma cells through a conserved binding site in the 3′UTR sequence." (PMID 30866509, 2019). "For that we assessed phosphorylation of ERK1/2, an effector protein of the RAS/RAF/MEK/ERK pathway, and MITF, a transcription factor determining the phenotypic state of melanoma cells." (PMID 31461993, 2019). "MITF is the central regulator of melanocyte and melanoma development and is known to confer survival advantage to melanoma tumors, especially under therapeutic challenges by driving multiple processes, including melanogenesis." (PMID 31547367, 2019). "Studies analyzing biopsies, derived from melanoma patients and xenograft samples, have shown that MITF expression was commonly upregulated in response to MAPK inhibition." (PMID 31416288, 2019). "The dependence of TFIIH-CAK on the sequence-specific transcriptional master regulators MITF or MYC constitutes a vulnerability in melanoma." (PMID 30651597, 2019). "The results so far suggest a complex relationship between MITF and the hypoxic response, with MITF able to affect the regulation of a set of hypoxia‐responsive genes in melanoma." (PMID 31207090, 2019). "A study integrating data from transcriptome, open chromatin and histone modification maps of melanoma cultures identified SOX10/MITF as regulator of the proliferative state and AP-1/TEAD as regulator of the invasive state." (PMID 31118886, 2019). "In 5–20% of human melanomas MITF undergoes genomic amplification and as such it acquires features of a lineage-survival oncogene." (PMID 30651597, 2019). "MITF plays a central role in melanoma progression and is recognized as the major driver of melanoma plasticity." (PMID 30699982, 2019). "MITF knockdown reduces the autophagy response to starvation in both melanocytes and melanoma cells, whereas MITF overexpression leads to an increased number of autophagosomes." (PMID 30705290, 2019). "Expression of NFATc2, MITF, AXL, ZEB1, SNAI1 (encoding SNAIL), and CDH2 (N-Cadherin) was then evaluated at the mRNA level, by qPCR, in a larger panel of 30 melanoma cell lines." (PMID 30710146, 2019). "Two modes of regulation are involved in the crosstalk between the Notch and MITF pathways in melanoma." (PMID 30699982, 2019). "MITF thus has a regulatory role within lysosomal function and autophagy in melanoma tumors, distinct from the related TFEB and TFE3 factors." (PMID 30705290, 2019). "Accordingly, MG132 treatment of melanoma cells caused an accumulation of CDK7 and rescued its expression under experimental depletion of MITF or c-MYC, the latter of which is an established target of several ubiquitin ligases." (PMID 30651597, 2019).